LCN2 (lipocalin 2)
Diseases named in the same sentence as LCN2 in open-access papers (continued):
Sharing a sentence is not in itself a finding about the gene and the disease.
Obesity (226 papers, 2009 to 2026). Accumulation of substantial excess body fat. "Increased LCN-2 expression is observed in the adipose tissue of obese individuals and is linked to obesity-related variables, including, among others, fasting glucose and the HOMA-IR index." (PMID 41227378, 2025). "In this context, high levels of Camp and Lcn2 are associated with muscle degeneration and can be implicated in Duchenne muscular dystrophy; Clstn3 is associated with obesity risk; and Irf4 knockout mice show better exercise capacity." (PMID 40002138, 2025). "In LCN2-deficient KO mice, lipocalin-2 deficiency protects mice from developing aging- and obesity-induced insulin resistance largely by modulating 12-lipoxygenase and TNF levels in adipose tissue." (PMID 41227378, 2025). "LCN2 is implicated in both acute and chronic inflammation and plays crucial pathogenic roles in diseases such as cancer, diabetes, obesity, and multiple sclerosis." (PMID 40830794, 2025). "LCN2 is likely involved in PCOS as obesity is linked to this condition and LCN2 is known to be strongly expressed by adipocytes." (PMID 38645429, 2024). "We had shown that MC4R and lipocalin-2 gene (LCN2) mutations were detected in 2.42% and 0.84%, respectively, of Spanish children with obesity." (PMID 37025415, 2023). "In clinical research, higher blood level of LCN2 was linked to obesity, insulin resistance, and dyslipidemia in people with type 2 diabetes." (PMID 37091847, 2023). "Highly downregulated genes at day 1 included genes associated with obesity including Col6a5 (collagen type VI alpha 5 chain), Fgg (Fibrinogen Gamma Chain), and adipokines Lcn2 (Lipocalin 2) and Retn (resistin) 32–34." (PMID 37770553, 2023). "Lipocalin-2 (LCN2), or neutrophil gelatinase-associated lipocalin (NGAL), is a glycoprotein from adipose tissue that modulates inflammation and metabolism and has been linked to obesity, hyperglycaemia, and insulin resistance." (PMID 38001998, 2023). "Differential protein lipocalin 2 (LCN2) is a member of the adipokine protein family and is associated with various diseases, including cancer, diabetes, and obesity." (PMID 38138996, 2023). "LCN2 can also act as a key mediator of HSC activation in leptin-deficient obesity via α-SMA/MMP9/STAT3 signaling and accelerated NASH." (PMID 37091847, 2023). "Lipocalin 2 (Lcn2) is an antimicrobial protein as well as adipokine associated with obesity and insulin resistance." (PMID 35812457, 2022). "LCN2, a neutrophil gelatinase-associated lipocalin, has been reported to play a critical role in inflammation in obesity." (PMID 36501079, 2022). "LCN2 deficiency protects against alcohol- and diet-induced liver inflammation and injury in mouse models of NASH, and LCN2-deficient mice are refractory to obesity-induced insulin resistance, adipose tissue inflammation and endothelial dysfunction." (PMID 36012166, 2022). "In clinical studies, higher blood lipocalin 2 levels are associated with obesity, insulin resistance, and dyslipidemia in patients with type 2 diabetes." (PMID 35216490, 2022). "Many studies have demonstrated that high plasma levels and expression for LCN2 were closely associated with obesity-induced metabolic complications such as NAFLD and diabetes." (PMID 36501079, 2022). "Another well-studied pro-inflammatory adipokine called lipocalin-2 showed sex-specific differences in circulating levels and association with obesity and obesity-related cardiometabolic malfunctions." (PMID 36012601, 2022). "Circulating LCN2 levels have been proposed as an inflammatory biomarker for obesity and its associated metabolic diseases." (PMID 35909571, 2022). "Loss- and gain-of-function experiments in gastric epithelial cells demonstrate that increased LCN2 protected against obesity associated gastric injury by inhibiting apoptosis and improving inflammatory state." (PMID 33637683, 2021).
Obesity (continued). "Despite these recent studies, the relationship between LCN2 expression and obesity associated gastric injury remains largely unclear." (PMID 33637683, 2021). "One important mediator in psoriasis is lipocalin-2 (LCN2), which is an antimicrobial protein and adipokine associated with insulin resistance, obesity and atherosclerosis." (PMID 34359859, 2021). "Our previous studies have reported that upregulating systemic and hippocampal LCN2 levels caused hippocampal atrophy and obesity-induced cognitive deficits in ob/ob mice." (PMID 34844610, 2021). "The pathological forms of adipose-derived LCN2 play a causal role in obesity-associated cardiometabolic and renal diseases." (PMID 34938273, 2021). "Recent studies show that Lcn2 is a proinflammatory marker positively associated with insulin resistance and obesity-related metabolic disorders." (PMID 33530524, 2021). "Measurement of serum Lcn2 is currently a principal diagnostic test in kidney failure and recently, use of Lcn2 as a biomarker for evaluating obesity-related cardiovascular diseases has also been proposed." (PMID 33530524, 2021). "Using in vivo models of chronic metabolic conditions, such as obesity or cancer, LCN2 was associated with hippocampal neurotoxicity and cognitive impairment via neuroinflammation, oxidative stress, and blood–brain barrier (BBB) leakage." (PMID 34829528, 2021). "Several studies have suggested that LCN2 is linked to inflammatory responses in metabolic disorders, including obesity, in which the pathway involves NF‐κB,157 C/EBP,158 and estrogen response elements." (PMID 33945675, 2021). "These are some of the examples that portray how obesity-caused LCN2 is a part of the tumorigenesis process." (PMID 33799862, 2021). "Lcn2 deficiency is characterized by increased food intake in mice, leading to insulin resistance and obesity." (PMID 34016950, 2021). "We further explored the potential functions of LCN2 upregulation in this context and demonstrated increased LCN2 protected against obesity associated gastric injury." (PMID 33637683, 2021). "The loss of LCN2 in osteoblasts or a global LCN2 deficiency in mice was reported to lead to obesity and insulin resistance because of enhanced food intake." (PMID 32544571, 2020). "Human studies have demonstrated that higher circulating LCN2 levels are associated with obesity, insulin resistance, and dyslipidemia in T2D patients, thereby proposing LCN2 as a serum marker for metabolic disorders." (PMID 32544571, 2020). "LCN2 has been associated with neurodegeneration, cancer metastasis, insulin resistance, obesity, and inflammatory responses." (PMID 30805373, 2019). "We expected that if LCN2 were an important anorexigenic factor, LCN2 deficiency during celastrol treatment should at least blunt celastrol’s appetite suppressing and anti-obesity effect at some level." (PMID 31488870, 2019). "Lipocalin-2 (LCN2), a protein secreted mainly by activated neutrophils, has been associated with neurodegeneration, obesity, and inflammatory responses." (PMID 30805373, 2019). "Most studies to date have focused on observational and epidemiological data on the involvement of LCN-2 in obesity and diabetic associated vascular complications." (PMID 31372314, 2019). "In that regard, it is noteworthy that lipocalin 2, a novel adipokine elevated in obesity subjects, has been shown to promote obesity-associated PDAC by stimulating the pro-inflammatory response in the TME." (PMID 31277269, 2019). "Compatible with these results, LCN2 deficiency was suggested to protect against HFD-induced obesity and insulin resistance." (PMID 31488870, 2019). "By contrast, deficiency of lipocalin-2 protects against dietary obesity-induced endothelial and cardiometabolic dysfunctions." (PMID 29731737, 2018). "Lipocalin 2 is an adipokine with potential importance in insulin resistance associated with obesity." (PMID 29048361, 2017).
Obesity (continued). "Lipocalin-2 (LCN2), a novel adipokine with catabolic activities in OA joints, contributes to the obesity and OA pathologies and is associated with other OA risk factors." (PMID 27385438, 2016). "Because inflammation strongly induces LCN2 expression in osteoblasts, and obesity and ageing, two major OA risk factors, are characterized by elevated LCN2 circulating levels, we investigated the effects of LCN2 on osteoblast metabolism." (PMID 27385438, 2016). "The impact of LCN2 for the formation of obesity, inflammation, and obesity-associated metabolic dysfunction was also shown in rat models after feeding with a high fructose diet for 4–8 weeks." (PMID 27729871, 2016). "On the other hand, lcn2, a novel proinflammatory adipokine is associated with obesity, insulin resistance, and hyperglycemia in humans." (PMID 27845741, 2016). "In conclusion, the data presented herein reveal a new facet of LCN2, the obesity-associated adipokine, as a catabolic factor in bone that is regulated in osteoblasts by inflammatory, catabolic, and anabolic factors." (PMID 27385438, 2016). "Accumulating evidence has linked Lcn2 to obesity, insulin resistance, inflammation, and metabolic diseases." (PMID 24818605, 2014). "WR increased the gene expression of AdipoR2, which can accelerate fatty acid oxidation and glucose intake, and WR also decreased protein expressions of LCN2, which has been implicated in the development of obesity and insulin resistance." (PMID 23434909, 2013). "The gene for the secreted glycoprotein lipocalin 2 (lcn2), which has been implicated in obesity and insulin resistance, was among those most responsive to alterations in CB1 signaling." (PMID 22073164, 2011). "Lcn2 (lipocalin 2), recently implicated in the development of obesity and insulin resistance, was markedly suppressed by UAG treatment." (PMID 20668691, 2010). "Elevated LCN-2 expression is observed in the adipose tissue of obese individuals and is positively associated with obesity-related parameters (e.g., BMI, waist circumference, body fat percentage), and insulin resistance (higher fasting glucose levels, the HOMA-IR index)." (PMID 41303567, 2025). "Notably, elevated serum LCN2 levels in ob/ob mice are associated with insulin resistance in humans, but this increase also appears to offer protection against obesity-induced insulin resistance." (PMID 39832399, 2025). "The upregulation of LCN2 in LsAAa samples could be a protective mechanism against the risk of obesity in these individuals." (PMID 39411310, 2024). "Furthermore, compared to normal individuals, patients with obesity have higher circulating levels of LCN2, and variations in LCN2 are inversely linked with variations in vasodilator function." (PMID 39558976, 2024). "Simultaneously, increased levels of apelin, chemerin, and lipocalin-2 suggest complex metabolic disorders that may be associated with obesity and IR." (PMID 39201400, 2024). "Given the common roles of LCN2 and GAL3 in the chronic inflammation associated with obesity and T2D, the functional relationships between adipose tissue macrophage-derived LCN2 and GAL3 and neuroinflammation would be expected in the diabetic brain with memory deficits." (PMID 38201988, 2024). "In addition, LCN2 acts as a key mediator of HSC activation in leptin-deficient obesity via α-SMA/MMP9/STAT3 signaling, further exacerbating NASH." (PMID 37784089, 2023). "LCN2 was recently found to be associated with obesity and its related metabolic comorbidities." (PMID 35034646, 2022). "Subsequent studies demonstrated that LCN2 was associated with various disorders, such as obesity." (PMID 35034646, 2022). "Furthermore, lipocalin 2, an antimicrobial peptide expressed in the intestine, modulated obesity-associated and metabolic dysregulation through SCFA production regulated by Dubosiella and Angelakisella43." (PMID 35256637, 2022). "Lipocalin-2 (LCN2) has a critical effect on obesity as well as its associated comorbidities." (PMID 35034646, 2022).
Obesity (continued). "Serum lipocalin-2 (LCN2) is closely associated with obesity, but its impact on weight loss after surgery is unknown." (PMID 35138515, 2022). "Lipocalin-2 (LCN2) has been implicated to have an important role in obesity and diabetes." (PMID 36501079, 2022). "As research has already proved the association between lipocalin-2 and obesity and obesity-related CVD, monoclonal anti-lipocalin-2 could be a feasible treatment option." (PMID 36012601, 2022). "A number of human disorders associated with obesity exhibit dysregulated expression of LCN2." (PMID 34064680, 2021). "Notably, lipocalin 2 (LCN2), a fat factor that was previously considered to be associated with obesity was recently found to exhibit an expression level in osteoblasts that is at least 10 times higher than that in white fat." (PMID 34650980, 2021). "LCN-2 has been associated with IR, DM and obesity-induced entothelial dysfunction." (PMID 33008659, 2020). "Because obesity is a risk factor for many cancers, LCN2 has become a focus of cancer research." (PMID 32575507, 2020). "In this context, LCN2 may be considered one of the mediators responsible for the low-level systemic inflammation observed in metabolic syndrome associated with obesity, representing a future therapeutic target." (PMID 33192583, 2020). "Our data support the anti-obesity effects of Lcn2 and thus Lcn2 deficiency may predispose to age-related development of metabolic disorders." (PMID 32883997, 2020). "Since diabetes, obesity and metabolic syndrome are all associated with underlying inflammation, Lcn2 treatment may potentially address several metabolic conditions." (PMID 32883997, 2020). "As such, LCN-2 is predominantly an osteoblast and adipocyte derived 25 kDa secreted glycoprotein which acts as a lipid chaperone positioning itself as a key pro-inflammatory link between obesity and associated metabolic disorders and vascular disease." (PMID 31372314, 2019). "Furthermore, LCN2-deficiency attenuated aging- and obesity-induced insulin resistance by inhibiting 12-lipoxygenase, an enzyme that metabolizes arachidonic acids, and tumor necrosis factor-α (TNF-α), a critical insulin resistance inducer." (PMID 31208019, 2019). "We thus reasoned that LCN2 might play a role in mediating celastrol’s anorexigenic and anti-obesity effect, such that LCN2 deficiency would reduce celastrol’s anorexigenic effects, and blunt the ability of celastrol to reduce body weight in DIO mice." (PMID 31488870, 2019). "LCN2 is an antimicrobial protein mainly secreted by activated neutrophils and associated with neurodegeneration, cancer metastasis, inflammatory responses, insulin resistance, obesity, and atherosclerotic disease." (PMID 30805373, 2019). "Since LCN2 is from the same family of proteins as RBP4, a lipid transporter whose synthesis increases with advancing years, age may affect the expression of LCN2 and influence the progression of diseases associated with obesity." (PMID 30915034, 2019). "Serum lipocalin-2 is closely associated with obesity and T2DM in humans." (PMID 29979770, 2018). "These lipocalin-2 changes had been linked to obesity and uncontrolled diabetes." (PMID 28709459, 2017). "We found that resistin and lipocalin-2/ngal, two adipokines involved in obesity-associated dysmetabolic state and inflammation, were similarly and inversely associated with TRAIL when this cytokine was detected within the first IV deciles of circulating levels." (PMID 29056829, 2017). "In experiments in Lcn2-deficient mice fed with a high fat diet to induce experimental steatosis, it was shown that the lack of LCN2 expression significantly potentiated diet-induced obesity, dyslipidemia, FLD, and insulin resistance." (PMID 27729871, 2016). "Obesity is associated with elevated serum lipocalin-2 levels." (PMID 21143924, 2010).
Obesity (continued). "Therefore, we speculated that OI patients could had insufficient secretion of LCN2 from bone, which could increase food intake and then increase the risk of obesity and disorders of glucose metabolism." (PMID 37326909, 2024). "Therefore, the study concluded that the reduction of ERα expression in adipose tissue induces obesity and is associated with increased adipocyte-specific LCN2 synthesis and higher LCN2 sensitivity in tumor cells, which in turn affects the course and severity of BCa." (PMID 39040042, 2024). "Consequently, LCN2 holds promise as a potential biomarker for obesity risk stratification (LCN2)." (PMID 39558976, 2024). "However, others have shown that XPro1595 can improve diet induced obesity (high-fat high-carbohydrate diet) and central-peripheral insulin impairment, in wild type mice partly through dampening of hepatic lipocalin-2, which is associated with and elevated in liver steatosis." (PMID 36186984, 2022). "For example, it has been proven that accumulated visceral fat, which is a hallmark of obesity, correlates with primary tumor recurrence, poor prognosis, and chemotherapeutic resistance In that setting, adipose tissue plays a significant role by excreting adipokines, with LCN2 being one of them." (PMID 33799862, 2021). "Therefore, the main objective of this study is to investigate whether LCN2 overexpression protects against obesity associated gastric injury and to explore the underlying mechanisms." (PMID 33637683, 2021). "Thus, Tim-1 deficiency may accelerate obesity-related liver inflammation and injury by upregulating LCN2, which warrants further investigation." (PMID 34675931, 2021). "On the other hand, there is a report indicating prominent expression of LCN2 in the liver and visceral adipose tissues, together with elevated blood levels, in obese mice due to excessive food intake, suggesting an association between low-grade inflammation and diet-induced obesity." (PMID 23875831, 2013). "The HFD mice were found to have higher levels of lipocalin-2 (LCN2) and galectin-3 (GAL3), two proteins which play inflammatory roles associated with obesity and diabetes." (PMID 39798403, 2025). "In females, LCN2 gene expression correlated positively with markers of obesity, insulin resistance, and hyperglycemia." (PMID 39511728, 2025). "LCN2 contributes to chronic inflammation, making it to be an important factor in several diseases including cancers, diabetes, obesity, and multiple sclerosis." (PMID 40989161, 2025). "The multifaceted functions of LCN2 make it a potential molecular target for the modulation of metabolic diseases, particularly obesity and type 2 diabetes (T2D)." (PMID 39808380, 2025). "As a result, circulating LCN2 concentrations have been proposed as a potential inflammatory biomarker in obesity and related metabolic conditions." (PMID 41303567, 2025). "All these results suggest that the postprandial increase in LCN2 levels in lean subjects as a satiety signal is impaired in individuals with obesity or severe overweight." (PMID 38035773, 2024). "The relationship between LCN2 and cancer casts some concern on the safety of LCN2 as a pharmaceutical intervention in the treatment of obesity and other metabolic syndromes." (PMID 38035773, 2024). "Lipocalin-2 (LCN2), a protein released by neutrophils and linked to inflammation, insulin resistance, and obesity, is higher in psoriasis than in the controls." (PMID 39063581, 2024). "Accordingly, plasmatic lipocalin-2, a glycoprotein involved in several obesity-related conditions as well as chronic inflammatory processes was found to be elevated in MS but not in partial or total GHD." (PMID 38379862, 2024). "It has been shown that LCN2 is upregulated during obesity and diabetes as a protective mechanism to counteract obesity-induced glucose intolerance by decreasing food intake and promoting adaptive β-cell proliferation." (PMID 39411310, 2024).